RHOA (ras homolog family member A)
Diseases named in the same sentence as RHOA in open-access papers (continued):
Sharing a sentence is not in itself a finding about the gene and the disease.
tumor (continued). "Finally, using both in vitro assays and an in vivo subcutaneous tumour xenograft model, we demonstrated that RhoA inhibition can hinder the activity of cancer‐related fibroblasts and weaken PC radiation resistance." (PMID 35277915, 2022). "Folate treatment above physiological levels supports epithelial to mesenchymal transition in experimental mouse tumor cells and silencing of RhoA and Rac1, which serve as immediate sensors of folate intracellularly, inhibited the effects of folate on cellular migratory and invasive abilities." (PMID 36198749, 2022). "miR-126 has been shown to act as a tumor suppressor via RhoA/ROCK inhibition in cancer cells." (PMID 33953222, 2021). "More importantly, we demonstrated that MITF regulates tumor progression in ccRCC cell via the RhoA/YAP signaling pathway; taken together, the results suggest that MITF could be a potential therapeutic target in ccRCC." (PMID 34208068, 2021). "Moreover, platelets are also involved in the activation of biomechanical pathways relevant to tumour cells such as RhoA or Yap, whose impact on metastasis was described in previous sections." (PMID 34241735, 2021). "As knocking down RhoA was able to suppress tumor growth, a combination of such knockdown and MPPa-PDT treatment may represent a viable synergistic antitumor strategy." (PMID 34627383, 2021). "Amoeboid tumor cells have a rounded morphology and pronounced RhoA activity." (PMID 33969605, 2021). "Therefore, we assumed that RhoA, indirectly regulated by circUBE2K, played a crucial role in tumor migration and metastasis." (PMID 34285193, 2021). "More recently, sequencing studies have raised the possibility that RhoA may have a tumor suppression tumor function." (PMID 35076580, 2021). "Regulation of RhoA stability by Cullin3 ubiquitin ligases is also observed in tumor cells." (PMID 34136490, 2021). "Therefore, the contribution of ZFAS1/miR-3924 in tumor metastasis via the RHOA/ROCK2 pathway was reported, confirming its potential regulatory effect on RHO GTPase members." (PMID 34771549, 2021). "RhoA, one of the most extensively studied members of the Rho family of small GTPase, is also involved in tumor cell migration and invasion, as well as fibrosis induction, both of which are prevented by curcumin through reversion of the epithelial–mesenchymal transition." (PMID 34445271, 2021). "Yet recent high-throughput sequencing efforts have identified loss-of-function mutations in RhoA9–12, and negative RhoA regulators, RhoGAPs, as oncogenes suggesting a tumor suppressive role of RhoA13,14." (PMID 34465801, 2021). "Here we show that the RKIP-mediated inhibition of CCL5 expression and F4/80+ cells tumor infiltration can be reversed by silencing of of RhoA expression suggesting RKIP may regulate CCL5 expression through RhoA GTPases." (PMID 34465801, 2021). "Reductions in RhoA-GTP in the residual xenografts paralleled the reductions in tumor weight." (PMID 34862367, 2021). "Indeed, tumor cells can remodel rigid substrates using RhoA-integrin-mediated cytoskeletal tensile forces, to form highly aligned and packed fibrotic areas perpendicular to the boundary of a tumor, facilitating cell invasion." (PMID 33673091, 2021). "Also, via the Rac1/RhoA-p38MAPK signaling pathway, IL-8 was found to promote endothelial cell migratory activity, and thereby promoting tumor angiogenesis." (PMID 34294770, 2021). "Other signatures were also identified in this analysis that implicates previously unreported processes in Vκ*MYC disease biology including signatures related to knockdown of the tumour suppressor TCF21, KRAS mutations, and constitutive activation of the RHOA oncogene." (PMID 34732728, 2021). "While RhoA activation has been shown to promote certain aspects of tumorigenesis in vitro and in vivo, in some contexts it has also been shown to inhibit particular tumor functions." (PMID 34627383, 2021).
tumor (continued). "When taken up by endothelial cells, circ‐IRAS increases endothelial monolayer permeability and promotes tumour invasion and migration through sponging miR‐122 and upregulating the expression level and activity of RhoA, which further increases F‐actin and decreases ZO‐1." (PMID 34898043, 2021). "Therefore, it is of interest to determine if Rac1-induced tumor formation can be avoided with RhoA or YAP/TAZ inhibition." (PMID 34062912, 2021). "However, some genetic mutations, such as those in HLA-B, MEF2A, RHOA, and NAV3, were associated with a high tumor proliferation index in this study." (PMID 33747936, 2021). "Furthermore, the elevated mRNA expression of RhoA and RhoC was accompanied by higher tumor stages and metastatic spread." (PMID 32443784, 2020). "Indeed, RhoA and RhoC are overexpressed in certain cancers and correlated with the aggressiveness of the tumor, i.e. the presence of metastases, and adverse clinical outcome." (PMID 33162807, 2020). "Moreover, combined with the rapamycin, ZA effectively suppressed the tumor recurrence after drug withdrawal and ZA inhibited the activity of GTPase RhoA by decreasing protein geranylgeranylation, resulting in changes of Yap nucleus translocation." (PMID 32063747, 2020). "RhoA/ROCK is proved to be a crucial signaling pathway in tumor progression." (PMID 33552977, 2020). "Mechanistic analyses have revealed that circ-IARS-positive exosomes may contribute to tumor invasion by (i) down-regulating miR-122 and ZO-1, (ii) up-regulating RhoA, RhoA-GTP, and F-actin and (iii) promoting focal adhesion." (PMID 32878635, 2020). "On the other hand, excessive degradation of RhoA also plays a role in inhibiting tumor invasion." (PMID 33377649, 2020). "Moreover, we described in detail how VEGF also activates RhoA, Rac1, and Cdc42 contributing thus to tumor motility and invasion." (PMID 32377503, 2020). "However, to our surprise, Humphries et al55 found that downregulation of ARHGAP18 by miR‐200b inhibited metastasis of TNBC by increasing the activation of RhoA, suggesting the tumour suppressive role of RhoA in TNBC." (PMID 32249490, 2020). "RhoA may play contradictory roles in tumorigenesis; several studies have attributed tumor suppressor characteristics to RhoA." (PMID 32244355, 2020). "The better effect of simvastatin may come from its target, RhoA, through which the mTORC2 could regulate the actin cytoskeleton, revealing the unneglected role of mTORC2 in tumor migration and invasiveness." (PMID 33072782, 2020). "Despite the fact that the SF formation was suppressed by RhoA-DN in tumor cells, it is worth investigating the hypothesis that the tumor suppressive role of RhoA, resulting in unaltered tumor cell proliferation." (PMID 33158289, 2020). "Meanwhile, there is still a possibility that FAK may act downstream of the integrin-RhoA pathway during tumor progression or metastasis of NSCLC." (PMID 32793596, 2020). "Thus, RhoA and RhoC are generally believed to act as tumor promoters, whereas the role of RhoB in human cancer is somewhat controversial." (PMID 32392742, 2020). "This suggests that RhoA plays an essential role in the invasion of neoplasms." (PMID 32731493, 2020). "However, less has been explored as to the regulation of periFN matrix assembly by RhoA/stress fiber on adherent tumor cells." (PMID 33158289, 2020). "The expression of RhoA was inversely correlated with that of miR-146 in BC cell lines and it was suggested that this miRNA functions as a tumor suppressor in BCCs, which was corroborated by the fact that its downregulation increased the migration of BCCs via upregulation of RhoA." (PMID 32731349, 2020). "Among of these members, RhoA has been lucubrated with its downstream target, Rho-associated coiled-coil kinase 1 (ROCK1) and researches have elucidated RhoA/ROCK1 pathway are related to EMT process and tumor metastasis." (PMID 32546278, 2020).
tumor (continued). "Particularly for the tumor cells, ithas been reported that their metastatic potential is relatedto actin skeleton arrangement and remodeling.In addition, to investigate cytoskeleton changes in themolecular level, we examined gene expression of VIMand RHOA." (PMID 31606974, 2020). "Altogether, RhoA stimulation might represent a mechanism for reducing liver tumorigenesis and for halting the circulation of tumor cells in hematogenous metastatic disease." (PMID 33302361, 2020). "It has been suggested that RhoA expression may correlate not only with distant metastases, but also with local tumor progression and other factors such as OS and DFS." (PMID 31976530, 2020). "Similarly, CD44–hyaluronan interaction induces the expression of miR-10b, which upregulates RhoA and RhoC resulting in the cytoskeleton activation and increased tumor cell invasiveness." (PMID 33321819, 2020). "Our findings are in line with this research, and we suggest that RhoA may acts as a tumor suppressor in KRAS induced NSCLC." (PMID 32244355, 2020). "Constitutively expressed RhoA functions in tumor development." (PMID 31331053, 2019). "Cancer-associated fibrosis generates a dense and stiff extracellular matrix (ECM) leading to integrin activation in focal adhesions and RhoA-induced remodeling of the actin cytoskeleton, which in turn favors tumor cell survival, proliferation and tumor progression." (PMID 30538286, 2019). "Thus, in the present study the effects of mutant RHOA were evaluated by combining transcriptome analysis of the tumor and stromal components and pathological analysis using an orthotopic xenograft model." (PMID 31485674, 2019). "Moreover, the tumor-promoting role of RhoA was also demonstrated by two genomic spatial event (GSE) datasets (GSE10186 and GSE 54236), in which the P values were 0.039 and 0.024, respectively." (PMID 31339860, 2019). "We therefore determined whether FAK/RhoA signaling pathways are activated in AGTR1-overexpressing tumor cells." (PMID 31219799, 2019). "In previous studies, we established the tumor suppressor StarD13 (steroidogenic acute regulatory protein)-related lipid transfer domain 13) as a GTPase-activating protein (GAP) that specifically inhibits RhoA and Cdc42 in GBM cells and other tumor models." (PMID 31698752, 2019). "S1PR1 promoted tumor endothelial-dependent vessel and decreased VM formation via RhoA signaling." (PMID 30814488, 2019). "RhoA is an oncogene that induces tumor progression through enhancing carcinogenic cell proliferation, angiogenesis, invasion and metastasis, suggesting the development of RhoA inhibitors could be a great strategy to restrain cancer promotion and progression." (PMID 30884855, 2019). "In addition, increased blood vessel formation and infiltration of macrophages within the tumor mass were observed in the RHOA mutants." (PMID 31485674, 2019). "Moreover, RhoA inactivation by expressing a dominant negative RhoA (T19N) increases tumor growth and metastasis in colorectal and liver cancers." (PMID 30683844, 2019). "Since the hypoxic signature in mock/WT tumors was more enriched than that noted in the mutant tumors, we considered the involvement of angiogenesis and found that the RHOA mutants had higher levels of blood vessel formation and infiltration of macrophages into the tumor mass." (PMID 31485674, 2019). "The crucial role of RhoA activity in 3MC-mediated alterations in molecular phenotypes was genetically validated; constitutively active (CA) was overexpressed, and the results suggested that CA-RhoA attenuated the tumor-promoting effect of 3MC." (PMID 30872677, 2019). "In this study, we aimed to reveal the mechanisms underlying the tumor-promoting effects of 3MC in RECs, with a particular focus on HIF1α/HDAC1 and RhoA, and to determine whether simvastatin can prevent these effects." (PMID 30872677, 2019).
tumor (continued). "RhoA-ROCK, which could induce stress fiber formation with Rho GTPase family, is implicated in CAF-mediated remodeling of tumor microenvironment." (PMID 30921404, 2019). "However, contrasting reports have been published on the role of RhoA–ROCK pathway in tumor invasion and metastasis." (PMID 30683844, 2019). "To determine whether S1PR1 promoted tumor angiogenesis and decreased VM formation via RhoA signaling, we used a RhoA inhibitor to block the separation of VE-cadherin and β-catenin in the tube formation assays." (PMID 30814488, 2019). "Because of its specificity for RhoA, Smurf1 also plays a role in tumor migration and invasion." (PMID 31248165, 2019). "Additional analyses revealed that circ-IARS enters HUVECs through exosomes and that circ-IARS acts as a sponge to absorb miR-122, increases RhoA activity and F-actin expression, reduces ZO-1 expression, enhances endothelial monolayer permeability, and promotes tumor invasion and metastasis." (PMID 30064461, 2018). "After 2 weeks of implantation, when the mice had a tumor volume of 20 mm3, the mice were treated with 100 μL of anti-RhoA (85 nM), anti-RhoC (85 nM) siRNA and cytofectin containing excipient as a control intratumarally at a 3-day interval over a period of 20 days." (PMID 29861465, 2018). "Thus, targeting PTP4A3, upstream of RhoA, can have multi-faceted anti-tumor and anti-metastatic effects." (PMID 29492190, 2018). "The anti-RhoA siRNA inhibited tumor growth in a dose-dependent manner." (PMID 29861465, 2018). "For instance, it was shown that RhoA and Rac1 can cooperate with Ras and Raf in tumor progression." (PMID 30544828, 2018). "RhoA and RhoC are the key drivers for a series of pathologies of cancer, including cell motility, proliferation, apoptosis inhibition, cell cycle progression, invasion, metastasis and inflammation of tumor cells." (PMID 29861465, 2018). "However, the roles of the CLOCK and BMAL1 genes in the regulation of tumor progression via the RHOA-ROCK-CFL pathway remain largely unclear." (PMID 30287810, 2018). "Interestingly, RhoA staining was more intense in the tumour centre compared to the invasion front, which raises some questions concerning its function: E-Cad was reported to downregulate RhoA and, in turn, reduce migration." (PMID 29976164, 2018). "This subset of proteins was particularly enriched in proteins involved in tumor metastasis and malignancy, such as proteins from the canonical actin cytoskeleton signaling, including several members of the RhoA/RhoGDI signaling pathway (ACTR2, EZR, MSM, PFN, GDI2)." (PMID 29872504, 2018). "RhoA in tumour centres probably have an additional function other than migration." (PMID 29976164, 2018). "Net1 is required for maximal RhoA activation within tumors and for primary tumor cell motility." (PMID 29769144, 2018). "Regarding pathway assignments of at least 20 HRO tumours, 10 top-ranked genes, of which 9 were lost in 3p, were linked with 7 to 45 pathways (n = 280) comprising RAF1 (45 PWs), RHOA (25 PWs), IPTR1 (22 PWs), CACNA1D, ITGA9 (8PWs), WNT7A (8 PWs) TLR9 (7PWS9, LAMB2 (7 PWs) and ARPC4 (6 PWs)." (PMID 28486536, 2017). "Statins are also known to have anti-proliferative effects in certain tumor cell types and this effect is attributed in part to reduction of the isoprenylation of proteins involved in cell signal transduction such as Ras and RhoA." (PMID 28261092, 2017). "Therefore, the aim of this study was to investigate the effect of hypoxia on the expression of HIF-1α, RhoA, cdc42 and Rac1, RhoA activation, cell proliferation and migration using five tumor cell lines of different tissue origin." (PMID 28562340, 2017). "Although hypoxic conditions have been shown to increase tumor cell motility and aggressiveness through the activation of small GTPases, the cell-type dependence of the expression and activation of RhoA, cdc42 or Rac1 is unknown." (PMID 28562340, 2017).
tumor (continued). "In addition, studies indicated hypoxia promoted tumor cell motility via RhoA and ROCK1 signaling pathways." (PMID 28184030, 2017). "Moreover, previous studies suggested that FBXW7 suppressed EMT of tumor cells by targeting c-Myc, Notch, mTOR and RhoA signaling pathway." (PMID 28716020, 2017). "Accordingly, we measured the proliferation, migration, RhoA activation, the mRNA and protein levels of hypoxia inducible factor-1alpha (HIF-1α) and three small G-proteins, Rac1, cdc42 and RhoA in a panel of five human tumor cell lines under normoxic and hypoxic conditions." (PMID 28562340, 2017). "LRP1B is a tumor suppressor and may regulate cell motility via the RhoA/Cdc42 pathway and actin cytoskeleton reorganization, but the exact role of LRP1B in HCC development has not been reported." (PMID 29117265, 2017). "In other words, exosomes from more aggressive cells may be able to accelerate tumor progression within a heterogeneous primary tumor, by activating the RhoA/ROCK signaling pathway in cells that uptake them." (PMID 28680152, 2017). "Further analysis of MTI/RhoA-dependence of cancer cell adhesion may provide clues to the future development of chemotherapy to suppress tumor dispersion." (PMID 29184140, 2017). "The intracellular mechanisms of rounded tumor cell migration delineated so far have been centered upon the suppressor and activator signals that regulate RhoA-ROCK and myosin light chain-2 (MLC2)-dependent actinomyosin-based contractility, cytoskeletal remodeling and dynamic cell adhesion events." (PMID 26567111, 2016). "Although until recently RHOA has never been reported to be mutated in human cancers, its overexpression and association with tumor progression have been reported in various cancers." (PMID 25823974, 2016). "Importantly, activation of the Par6/Smurf1/RhoA pathway which leads to RhoA degradation has been shown to be required for maintaining tumor cell motility and epicardial cell invasion." (PMID 27223264, 2016). "Observations suggest that activated RhoA is found in the nucleus upon irradiation of tumor cells." (PMID 27597870, 2016). "Moreover, RHOA perturbation resulted in strong inhibition of GC cell proliferation and tumor growth." (PMID 27806312, 2016). "However, a recent study reported that ERR1, whose high expression correlates with tumor aggressiveness and poor prognosis, decreases the stability and activity of the RhoA protein and promotes cell migration." (PMID 27713154, 2016). "RhoA has been shown to regulate tumor progression in several tumors." (PMID 27597870, 2016). "This could be due to differences in the expression of downstream effectors in different tissue types, or different requirements for RhoA throughout the life-cycle of a tumor." (PMID 27104658, 2016). "The association between RhoA/ROCK/Cav-1 and the genesis of tumor have raised increasing concerns." (PMID 26066055, 2015). "Additionally, samples from cirrhotic patients and controls were collected at liver transplantations and tumor resections were analyzed for RhoA and c-SRC protein expression by Western Blot." (PMID 26696895, 2015). "This study suggests that targeting of RhoA alone may allow for compensation and a paradoxical exacerbation of neoplasia, while simultaneous targeting of both RhoA and RhoC is likely to lead to more favorable outcomes." (PMID 26030593, 2015). "This complex attracts the ABL2 tyrosine kinase, which activates p190RhoGAP, resulting in the inactivation of RhoA, a small GTPase that converts GTP to GDP, leading to depolymerization of F-actin and the loss of stress fibers with an associated diminished EC and tumor cell migratory response." (PMID 26156437, 2015). "Next we sought to determine whether RhoA is required for oncogenic K-Ras-induced tumor initiation in vivo." (PMID 26030593, 2015).